DNMT3A (DNA methyltransferase 3 alpha)
Diseases named in the same sentence as DNMT3A in open-access papers (continued):
Sharing a sentence is not in itself a finding about the gene and the disease.
papillary thyroid carcinoma (4 papers, 2020 to 2026). "In 1.2% of papillary thyroid carcinoma cases, mutations and/or loss of DNMT3A expression were associated with aggressive clinical course and poor outcome." (PMID 34572812, 2021). "Herein, we describe and study an additional patient developing multiple head & neck PGLs and papillary thyroid carcinoma (PTC) who carries a new gain-of-function DNMT3A germline variant." (PMID 33182397, 2020). "Here we describe a novel DNMT3A germline variant identified by whole-exome sequencing in a patient with multiple paragangliomas and papillary thyroid carcinoma." (PMID 33182397, 2020). "Here, whole-exome sequencing identifies a novel germline DNMT3A variant (p.Gly332Arg) in a patient with bilateral carotid paragangliomas, papillary thyroid carcinoma and idiopathic intellectual disability." (PMID 33182397, 2020).
postmenopausal osteoporosis (4 papers, 2016 to 2025). Metabolic disorder associated with fractures of the femoral neck, vertebrae, and distal forearm. "Treatment with TF-3 resulted in a reduction of number of activated osteoclasts, a higher bone mass, and protection against bone loss, suggesting that the inhibition of Dnmt3a could be a beneficial strategy for preventing bone loss and controlling postmenopausal osteoporosis." (PMID 27529237, 2016). "Furthermore, they investigated the possibility that targeted Dnmt3a inhibition may have a positive effect in preventing bone loss, by administration of the Dnmt3a inhibitor theaflavin-3,3′-digallate (TF-3) to ovariectomized female mice, as a model of postmenopausal osteoporosis." (PMID 27529237, 2016). "Studies show that osteocyte ferroptosis, regulated by the Nrf2 pathway, affects RANKL expression via Dnmt3a-mediated DNA methylation of the RANKL promoter, influencing OC formation and contributing to postmenopausal osteoporosis (PMOP)." (PMID 40678144, 2025).
retinoblastoma (4 papers, 2017 to 2025). A malignant tumor that originates in the nuclear layer of the retina. "The study also mentions the connection between BIRC5 (survinin) and DNA methylation in retinoblastoma regulated by Dnmt1, Dnmt3a, and Dnmt3b." (PMID 41150792, 2025). "In support of this possibility, DNMT3A and DNMT3B were found to be highly expressed in Y79 and primary retinoblastoma." (PMID 28467809, 2017).
rhabdomyosarcoma (4 papers, 2021 to 2025). A rare aggressive malignant mesenchymal neoplasm arising from skeletal muscle. "The only previous study investigating the influence of DNMT3A and DNMT3B expression on radiosensitivity found a lower radiosensitivity in embryonal rhabdomyosarcoma cells in case of overexpression." (PMID 40507223, 2025).
rheumatoid arthritis (4 papers, 2020 to 2025). A chronic, systemic autoimmune disorder characterized by inflammation in the synovial membranes and articular surfaces. "Rheumatoid arthritis (RA) patients also demonstrate an elevated CHIP prevalence, especially in older patients, with DNMT3A and TET2 mutations prevalent." (PMID 39997650, 2025). "Nakano and colleagues measured the protein levels of DNMT1 and DNMT3A in fibroblast-like synoviocytes (FLS) from rheumatoid arthritis (RA) and OA patients." (PMID 32140068, 2020). "Similarly, rheumatoid arthritis (RA) patients have a 17% higher prevalence of CHIP, which increases to 25% in individuals aged 70-79 years, with DNMT3A and TET2 mutations being the most frequent." (PMID 38162500, 2023).
skin cancer (4 papers, 2017 to 2023). "Importantly, our results show that PPAR-γ is partially responsible for promoting tumorigenesis in Dnmt3a-deficient epidermis, which considering that human skin tumors express lower levels of Dnmt3a, might provide us with a new therapeutic antitumor avenue against squamous cell carcinomas." (PMID 28425913, 2017). "Although the development of two uncommon cancers is not direct evidence that DNMT3A haploinsufficiency generates a premalignant state for skin tumors, preclinical models have suggested that Dnmt3a deficiency causes proliferative priming as a potential mechanism." (PMID 37160317, 2023).
squamous cell carcinoma (4 papers, 2014 to 2023). A carcinoma arising from squamous epithelial cells. "Although these differences were similar to the ones observed in single Dnmt3a-cKO mice, DcKO mice formed aggressive squamous cell carcinomas at a higher frequency as compared to the single cKOs of Dnmt3a or Dnmt3b." (PMID 28425913, 2017). "Although Dnmt3a-cKO animals showed a strong increase in tumor initiation and burden, they developed the same percentage of squamous cell carcinomas than wild-type mice." (PMID 28425913, 2017). "Only upon combined deletion of Dnmt3a and Dnmt3b, squamous carcinomas become more aggressive and metastatic." (PMID 28425913, 2017). "Altogether, we demonstrate that Dnmt3a and Dnmt3b protect the epidermis from tumorigenesis and that squamous carcinomas are sensitive to inhibition of PPAR-γ." (PMID 28425913, 2017). "However, both Dnmt3a and Dnmt3b repress the malignant transformation of epidermal cells into aggressive squamous cell carcinomas." (PMID 28425913, 2017). "When DNMT3A and DNMT3B are both deleted, the squamous cell carcinomas become more invasive and metastatic." (PMID 32751889, 2020). "In mice treated with skin cancer-inducing chemicals, deletion of DNMT3A increases the number of carcinogen-induced squamous cell carcinomas without affecting tumor progression." (PMID 32751889, 2020).
ulcerative colitis (4 papers, 2018 to 2024). An inflammatory bowel disease involving the mucosal surface of the large intestine and rectum. "Moreover, a study involving ulcerative colitis patients found higher levels of IFN-γ in their serum, especially among those with DNMT3A-CH, implying a potential link between DNMT3A-CH and IFN-γ." (PMID 39119355, 2024). "A sequencing analysis of peripheral blood mononuclear cell DNA from ulcerative colitis patients suggested that DNMT3a was involved in the regulation of UC, which has not been identified in UC patients or models." (PMID 35574272, 2022).
Wilms tumor (4 papers, 2021 to 2024). An embryonal neoplasm characterized by the presence of epithelial, mesenchymal, and blastema components. "The results revealed that circ0093740 promotes the Wilms tumor progression by sponging miR-136/145 which contributes to the upregulation of DNMT3A expression." (PMID 34168984, 2021). "We conducted qPCR analysis and found that DNMT3A was remarkably upregulated in Wilms tumor." (PMID 34168984, 2021). "DNMT3A was upregulated in Wilms tumor which contribute to the epigenetic changes of cancer cells." (PMID 34168984, 2021). "In addition, we conducted AGO2 related RIP assays which revealed circ0093740, miR-136/145 and DNMT3A were all enriched to AGO2 RNA binding protein in both SKNEP1 and G401 Wilms tumor cell lines." (PMID 34168984, 2021).
amyotrophic lateral sclerosis (3 papers, 2011 to 2020). Amyotrophic lateral sclerosis (ALS) is a neurodegenerative disease characterized by progressive muscular paralysis reflecting degeneration of motor neurons in the primary motor cortex, corticospinal tracts, brainstem and spinal cord. "The phenotype of these mice was similar to transgenic mouse models of amyotrophic lateral sclerosis (ALS), further implicating Dnmt3a in the pathogenesis of motor neuron degeneration." (PMID 23289056, 2011). "Because mitochondria have been implicated in the pathogenesis of amyotrophic lateral sclerosis (ALS), but the disease mechanisms are uncertain, we evaluated mitochondrial Dnmt3a and 5mC levels in human superoxide dismutase-1 (SOD1) transgenic mouse models of ALS." (PMID 24399935, 2013).
Arterial thrombosis (3 papers, 2024 to 2025). The formation of a blood clot inside an artery. "DNMT3A mutations, an independent risk factor for arterial thrombosis in MPN, leads to aggressive inflammatory transcriptome, enhance macrophage activity and stimulate proinflammatory T-cell polarization." (PMID 41153823, 2025). "In the whole cohort of patients, molecular classification identified PV/ET patients at higher risk of disease progression whereas DNMT3A/TET2/ASXL1 mutations were associated with higher risk of arterial thrombosis." (PMID 38263537, 2024). "The findings demonstrated the significance of DNMT3A mutations as an independent molecular risk factor for arterial thrombosis, highlighting the potential to include this somatic non-driver mutation in innovative thrombosis risk scores." (PMID 40287867, 2025).
asthma (3 papers, 2019 to 2025). "DNMT1 and DNMT3a, as DNA methyltransferase enzymes as writer proteins, play a key role in methylating DNA, contributing to the epigenetic alterations associated with asthma pathogenesis." (PMID 41008562, 2025). "Thus, DNMT3a acts as an epigenetic brake on Th2 cytokine expression, and its deficiency may exacerbate asthma pathogenesis by promoting IL-13–driven inflammation." (PMID 41008562, 2025). "These insights are essential for understanding the role of DNMT1 DNMT3a in epigenetic regulation relevant to asthma pathogenesis." (PMID 41008562, 2025). "It was concluded that DNMT3a and DNMT3b mediated de novo methylation of miR-23b promotor, which plays a vital role in EMT and airway remodeling in asthma." (PMID 35058921, 2021).
B cell lymphomas (3 papers, 2014 to 2021). "We identified 666 mutations from 262 genes in baseline cfDNAs from 79 B-cell lymphoma patients, and found some genes were preferentially mutated in our cohort such as GNAQ, GNAS, H3F3A, DNMT3A, HLA-A, and HLA-B." (PMID 34926267, 2021). "Our results show that DNMT1, DNMT3a/b are up-regulated in B-cell lymphomas, and that this relies on down-regulation of specific miRNAs." (PMID 25705251, 2014). "In this paper, we investigated the expression of DNMT family members (DNMT1, DNMT3a/b) in primary cases of aggressive B-cell lymphomas of HIV-positive subjects." (PMID 25705251, 2014). "Our results confirmed the activation of DNMT1 by HIV in vivo, and reported for the first time a marked up-regulation of DNMT3a and DNMT3b in HIV-positive aggressive B-cell lymphomas." (PMID 25705251, 2014). "HIV is reported to induce the expression of DNMT1 in vitro, though no information is available about its effect on DNMT3a/b, and about their expression in HIV-positive B-cell lymphomas." (PMID 25705251, 2014).
Cerebral ischemia (3 papers, 2021 to 2025). Restriction of arterial blood supply to the brain associated with insufficient oxygenation to support the metabolic requirements of the tissue. "DNMT3A is involved in the regulation of mitochondrial autophagy following cerebral ischemia-reperfusion injury." (PMID 40356977, 2025). "Taken together, cerebral ischemia increased DNMT3A levels in the brain, particularly in the penumbral area." (PMID 39006763, 2024). "RG108 treatment for DNMT3A inhibition resulted in an expansion of infarct volume and deterioration of neurological deficits after cerebral ischemia in mice." (PMID 39006763, 2024).
Cirrhosis (3 papers, 2019 to 2026). A chronic disorder of the liver in which liver tissue becomes scarred and is partially replaced by regenerative nodules and fibrotic tissue resulting in loss of liver function. "In HCV-related cohorts, circulating DNMT3A mRNA has shown strong diagnostic performance in distinguishing HCC from cirrhosis, with an AUC of 0.958 at a defined cutoff, and with sensitivity and specificity values of 80.8% and 95.6%, respectively." (PMID 41465346, 2025). "mRNA levels of DNMT1 and DNMT3A are significantly higher in noncancerous livers affected by chronic hepatitis or cirrhosis compared with histologically normal livers, and these levels rise further in HCC." (PMID 41465346, 2025). "The number of methylated genes and the mRNA levels of DNMT1, DNMT3a and DNMT3b were shown to be increased progressively from normal liver, chronic hepatitis/cirrhosis to HCC." (PMID 31771617, 2019).
colorectal tumor (3 papers, 2014 to 2024). "More importantly, we found that the expression level of DNMT3A in colorectal tumor (n = 275) is higher than in normal tissue (n = 41) by analyzing TCGA database." (PMID 39284825, 2024). "DNMT3A expression was increased in 12/20 (60%) of the colorectal tumors (P<0.05)." (PMID 25272045, 2014).
dementia (3 papers, 2020 to 2022). Loss of intellectual abilities interfering with an individual's social and occupational functions. "We previously demonstrated that DNMT1 mRNA levels are not regulated in buffy coat samples from patients with AD, whereas DNMT3a expression is downregulated in buffy coats from dementia patients and in the brain of saline-treated APP/BIN1/COPS5 AD mice." (PMID 36432638, 2022). "As we observed a decrease in DNMT3a expression in human blood samples of patients with Dementia, we also analyzed the expression of this gene in 3xTg-AD mice brain." (PMID 32210102, 2020). "The importance of methylation and hydroxymethylation reduction is stressed by the finding that DNMT3a mRNA levels are also downregulated in buffy coats of patients with Dementia (n = 25)." (PMID 32210102, 2020). "DNMT3a expression in NDD patients with dementia decreased by 80% compared to healthy subjects." (PMID 35008438, 2021). "DNMT3a expression was furthermore reduced in buffy coat samples from patients with dementia." (PMID 35008438, 2021). "Interestingly, a significant decrease in DNMT3a expression is observed in blood samples from patients with different types of dementia." (PMID 32210102, 2020). "DNMT3a expression was also found to be downregulated in patients with different types of Dementia." (PMID 32210102, 2020). "However, DNMT3a expression was significantly downregulated in patients with dementia." (PMID 32210102, 2020). "We previously showed that DNMT3a expression is downregulated in patients with various types of dementia, but not in patients with PD {35}." (PMID 35008438, 2021). "In samples from patients with dementia, DNMT3a expression was lower in females, but without significant differences (p-value 0.0775)." (PMID 32210102, 2020).
diabetic nephropathy (3 papers, 2016 to 2021). "Gondaliya et al26 found that miR29b might effectively target DNMT3B, DNMT1 and DNMT3A contributing in the development of diabetic nephropathy in renal proximal tubular cells." (PMID 33484504, 2021). "In summary, high-glucose stimulation activates ERK/MEK pathway and subsequently increases the cytoplasmic translocation of Dnmt3a, which contributes to the hypo-methylation of CTGF promoter and the increased expression of CTGF in diabetic nephropathy." (PMID 27364355, 2016). "In conclusion, high glucose induces cytoplasmic translocation of Dnmt3a, possibly through activating ERK/MAPK signalling pathway, which contributes to the decreased binding of Dnmt3a on CTGF promoter and the subsequent CTGF hypo-methylation in diabetic nephropathy." (PMID 27364355, 2016).
diffuse large B-cell lymphoma (3 papers, 2018 to 2025). "However, in diffuse large B‐cell lymphoma (DLBCL), Tanager and colleagues confirmed that although most tumors showed a reduction in 5hmC, only approximately half harboured mutations in epigenetic regulators such as TET2 and DNMT3A." (PMID 40116537, 2025).
Down syndrome (3 papers, 2019 to 2023). "The aim of this study was to investigate the association between the MTHFR rs1801133, MTHFR rs1801131, MTRR rs1801394, DNMT1 rs2228611, DNMT3A rs1550117, DNMT3B rs1569686, and DNMT3B rs2424913 gene polymorphisms and congenital heart defects in Down syndrome (DS) individuals." (PMID 36980848, 2023).
epilepsy (3 papers, 2019 to 2025). A brain disorder characterized by episodes of abnormally increased neuronal discharge resulting in transient episodes of sensory or motor neurological dysfunction, or psychic dysfunction. "Vagus nerve stimulation (VNS) reduces the number of SRSs in rats with epilepsy with concomitant decrease of 5‐mC, DNMT1, DNMT3A, METTL3, and METTL14, as well as increase of 5‐hmC." (PMID 40534269, 2025). "We conclude that VNS reduces the number of SRSs in a rat model of epilepsy, concurrently reducing the expression of 5‐mC, DNMT1, DNMT3A, METTL3, and METTL14, as well as the increase of 5‐hmC." (PMID 40534269, 2025).
Glucose intolerance (3 papers, 2017 to 2021). Glucose intolerance (GI) can be defined as dysglycemia that comprises both prediabetes and diabetes. "We next wanted to determine if skeletal muscle DNMT3A had a role in high fat diet (HFD)-induced glucose intolerance or adiposity as a previous investigation found that DNMT3A ablation in adipose tissue improved glucose tolerance in mice fed a HFD but not in chow-fed mice." (PMID 33513138, 2021).
hearing loss (3 papers, 2018 to 2025). "Of note, rare variants in DNMT1 and DNMT3A genes have also been reported in noise-induced hearing loss." (PMID 38970134, 2024). "The largest cohort study (n = 1053) conducted in Chinese adults showed polymorphisms in both DNMT1 and DNMT3A that were implicated in noise-induced hearing loss (NIHL)." (PMID 38970134, 2024). "This study was conducted to explore the effects of DNMT1 and DNMT3A polymorphisms on susceptibility to noise-induced hearing loss (NIHL) in Chinese workers." (PMID 30111769, 2018). "This balanced reduction in DNMT3A activity could help preserve the expression of genes essential for maintaining the structural and functional integrity of the cochlea, protecting against the cellular stress and damage that lead to hearing loss." (PMID 40428348, 2025). "The discovery that methylation at the promoter regions of DNMT3A, UQCR11, POLQ, and SIGLEC5 has a protective effect against hearing loss suggests a multifaceted mechanism by which epigenetic regulation preserves auditory function." (PMID 40428348, 2025).
Hepatic steatosis (3 papers, 2020 to 2023). Steatosis is a term used to denote lipid accumulation within hepatocytes. "In the liver, it is previously reported that development of hepatic steatosis was accompanied by changes in Dnmt1 and Dnmt3a expression." (PMID 35745277, 2022). "Indeed, we found that inhibiting DNA methylation by genetic deletion of Dnmt1 or Dnmt3a dramatically ameliorates hepatic steatosis in diet‐induced obese mice." (PMID 37282749, 2023). "Further, in obese mice, decreased lipogenic gene expression, de novo lipogenesis, and decreased hepatic steatosis and glucose tolerance mediated by SHP were also dependent on hepatic DNMT3A." (PMID 33235221, 2020).
Heyn-Sproul-Jackson syndrome (3 papers, 2023 to 2026). "We demonstrate that DNMT3A gain-of-function mutations in Heyn-Sproul-Jackson syndrome recapitulate age-related gains in DNA methylation (DNAme), cause multilineage stem cell dysfunction, and phenocopy aspects of aging in humans and mice." (PMID 42286141, 2026). "In contrast, heterozygous DNMT3A gain-of-function mutations cause Heyn-Sproul-Jackson syndrome (HESJAS) which is characterised by microcephalic dwarfism and hypermethylation of Polycomb-marked DNA methylation valleys." (PMID 39446312, 2024). "In contrast, gain-of-function (GoF) variants of DNMT3A were shown to cause Heyn-Sproul-Jackson syndrome (HESJAS; OMIM #618724), a very rare condition reported in only three patients to date, all of whom presented with microcephalic primordial dwarfism." (PMID 36814905, 2023).
ICF syndrome (3 papers, 2020 to 2023). "The divergent substrate preference between DNMT3A and DNMT3B provides an explanation for site-specific epigenomic alterations seen in ICF syndrome with DNMT3B mutations." (PMID 32620778, 2020).